CCK (cholecystokinin)
Diseases named in the same sentence as CCK in open-access papers (continued):
Sharing a sentence is not in itself a finding about the gene and the disease.
Insulin resistance (20 papers, 2015 to 2025). Increased resistance towards insulin, that is, diminished effectiveness of insulin in reducing blood glucose levels. "Insulin resistance increases the secretion of cholesterol, reduces the synthesis of bile acid, and lowers the cholecystokinin response, slowing gallbladder movement and causing cholesterol to remain in the gallbladder, thereby increasing the risk of stones and polyp formation." (PMID 35547207, 2022). "Animal models of insulin resistance—including high-fat-diet-fed and genetically obese mice—have been primarily used to investigate CCK expression in pancreatic islets, showing its upregulation and increased local CCK production during acute metabolic stress." (PMID 40864811, 2025). "Based on the findings, the authors believe that there is potential for using CCK agonists to regulate the function of WAT under conditions of insulin resistance." (PMID 39408213, 2024). "The results of the reviewed studies indicate that the use of CCK agonists may provide therapeutic effects in the treatment of insulin resistance." (PMID 39408213, 2024). "Insulin resistance increases cholesterol secretion, decreases bile acid synthesis, decreases cholecystokinin response, and slows gallbladder motility, leading to cholesterol retention in the gallbladder, thereby increasing the risk of gallbladder stone formation." (PMID 39315007, 2024). "CCK may positively influence lipid metabolism in adipose tissue, reduce systemic inflammation and decrease insulin resistance." (PMID 39408213, 2024). "In addition, inflammation induced upregulation of SOCS-3, a marker of leptin and insulin resistance, can result in impaired ability of satiety signals, such as cholecystokinin, to activate neurons in the hindbrain and reduce food intake." (PMID 27512604, 2016). "Since supraphysiological doses of CCK stimulate pancreatic insulin secretion, higher levels of circulating CCK induced by chronic palmitate treatment could be a compensatory response to insulin resistance in the prediabetic condition, which leads to hyperinsulinemia." (PMID 35887100, 2022). "Evidence of whether L-Phe reduces food intake; stimulates the release of CCK, PYY, or GLP-1; and is related to insulin resistance seems to vary across species of experiments and levels of L-Phe intake." (PMID 40588730, 2025). "Interestingly, the characteristic insulin resistance evoked by sustained high fat feeding did not appear to be appreciably improved by [Lys12Pal]Ex-4/CCK intervention." (PMID 34054734, 2021).
schizophrenia (18 papers, 2013 to 2025). A major psychotic disorder characterized by abnormalities in the perception or expression of reality. "Beyond that, several other neurotransmitters and neuropeptides, including oxytocin, serotonin, cortisol, GABA, cannabinoid, neuropeptide Y, neurotensin, cholecystokinin, corticotropin-releasing factor, and orexin, have been implicated in the neuropathophysiology of schizophrenia." (PMID 35806096, 2022). "A receptor gene for human CCK gene product (CCK-AR) may also be associated with positive symptoms of schizophrenia, particularly auditory hallucinations." (PMID 34573345, 2021). "Multiple differentially expressed genes (KCNIP4, GRM3, PRKG1, NPY for inh-C, and TRPC3 for inh-CCK) were related to glutamate reception and calcium channel activity, indicating these processes are altered within inhibitory midbrain neurons in schizophrenia." (PMID 39397771, 2025). "At the transcription level, gene expression changes in schizophrenia were mostly detected within the low abundant GABAergic (sub)populations, including inh-CCK and inh-C." (PMID 39397771, 2025). "The role of cholecystokinin in the metabolic syndrome of persons with schizophrenia warrants further investigation." (PMID 35806096, 2022). "For example, dysregulations of insulin, cortisol, glucagon, glucagon-like peptide 1, cholecystokinin, adiponectin, ghrelin, leptin, orexin, prolactin, and oxytocin have been observed during treatment with antipsychotics among persons with schizophrenia." (PMID 35806096, 2022). "Cholecystokinin-expressing GABAergic (CCK-GABA) neurons are thought to play an important role in pathologies such as schizophrenia, but their contributions to behavior in healthy states are poorly understood." (PMID 30834305, 2019). "Specifically, by modulating the activity of cholecystokinin-positive (CCK+) interneurons, 5-HT1BRs may influence cognitive processes vulnerable in schizophrenia." (PMID 40806385, 2025). "Notably, 5-HT3Rs are co-expressed with CB1 and α7 nicotinic receptors on CCK+ interneurons, all of which are dysregulated in schizophrenia." (PMID 40806385, 2025). "In the adult human brain, we found that IL-6 may form an interacting community with other proteins differentially overexpressed in the MTG, including CCK and NPY, which are also implicated in schizophrenia and other mental illnesses." (PMID 35353173, 2022). "In the case of schizophrenia, evidence suggests that dysregulated CCK-GABA neuron signaling may contribute to the pathogenesis of the disorder." (PMID 30834305, 2019). "If disrupted CCK-GABA neuron signaling contributes to the pathogenesis of schizophrenia, then activation of CCK-GABA neurons might prove therapeutic." (PMID 30834305, 2019). "Finally, it also deserves mention that CCK in dopaminergic mesolimbic neurons projecting to the frontal brain might be of relevance for the pathophysiology of schizophrenia." (PMID 40557463, 2025). "However, in contexts where the glutamatergic phenotype of CCK+VGluT3+INTs is amplified, they promote paradoxical network hyperexcitability which may be relevant to disorders involving GAD dysfunction such as schizophrenia or vitamin B6 deficiency." (PMID 32053107, 2020). "Moreover, the main receptor for NRG1 signaling, ErbB4, itself a schizophrenia risk gene (Schizophrenia Working Group of the Psychiatric Genomics Consortium, 2014), is expressed in PV+ and CCK+ GABAergic interneurons but not in glutamatergic pyramidal cells." (PMID 29740596, 2018). "In human studies of schizophrenia and animal models of the disorder, there is reduced expression of CCK and CB1 receptor markers as well as suppression of the cortical rhythms mediated by CCK-GABA neurons." (PMID 30834305, 2019). "Several disorders may involve disruption of CCK-GABA neuron signaling, including chronic stress and schizophrenia." (PMID 30834305, 2019).
schizophrenia (continued). "Thus, in patients with depression, schizophrenia, Parkinson's disease, and severe alcohol dependence, the cerebrospinal CCK concentrations are decreased but still overlapping with normal levels." (PMID 40557463, 2025). "CCK agonists that may be active in the treatment of schizophrenia should be nonselective or CCKR1 selective." (PMID 23986909, 2013). "Sham group, while being exposed to surgery, did not receive any invasive physiological manipulations; SDA model leaves half of the vagal efferents intact; CCK test to assess completeness of SDA procedure; Use of male rats only; No animal model of schizophrenia was used." (PMID 39881804, 2024).
panic attacks (14 papers, 2014 to 2025). "When it comes to the association of CCK with panic disorder, with a lifetime prevalence of 3.5% (5% in women and 2% in men), a couple of observations are worth remembering." (PMID 34577128, 2021). "Second, is peripheral intestinal CCK in plasma associated with panic disorder?" (PMID 34577128, 2021). "Nevertheless, it was unexpected that a simple intravenous bolus injection of the C-terminal tetrapeptide fragment of CCK should open the gates for decades of comprehensive studies of the role of CCK in panic disorder." (PMID 34577128, 2021). "The story of CCK and panic disorders, however, has left several open questions." (PMID 34577128, 2021). "You might even ask whether significant knowledge about the CCK-panic disorder link would exist today without the serendipitously discovered effect of CCK-4." (PMID 34577128, 2021).
functional dyspepsia (12 papers, 2007 to 2025). "Furthermore, CCK-1 receptor belongs to the family of GPCRs and has been shown to be associated with symptoms of dyspepsia, and hyperresponsiveness to CCK has been demonstrated in patients with FD." (PMID 31178907, 2019). "Interestingly, functional dyspepsia is also associated with disturbances in GI motility and circulating ghrelin, CCK and PYY concentrations." (PMID 30597915, 2018). "In functional dyspepsia patients, plasma CCK concentrations are positively correlated with the scores for nausea and pain." (PMID 35527812, 2022). "In functional dyspepsia, diet induced CCK release is increased, and the CCK-A receptor antagonist dexloxiglumide reduced gastric distension-induced symptoms in functional dyspepsia patients." (PMID 35527812, 2022). "CCK is known to inhibit food intake via the activation of chemosensitive vagal afferents and, in functional dyspepsia, high fat diet-induced CCK release is increased." (PMID 35527812, 2022). "It is known that plasma CCK levels are elevated in functional dyspepsia patients compared to healthy controls and that endogenously released CCK acts on vagal afferent mucosal terminals in the small intestine." (PMID 29674959, 2018). "In summary, lipid hypersensitivity in functional dyspepsia patients is mediated, at least in part, via CCK acting on CCK-1 receptors." (PMID 29674959, 2018). "It has been demonstrated that the plasma concentration of CCK is elevated in functional dyspepsia patients compared to healthy controls." (PMID 29674959, 2018). "Despite this reservation, loxiglumide (a CCK antagonist) has been shown to accelerate the GE of lipid-rich liquid meals in healthy subjects as well as patients with functional dyspepsia and irritable bowel syndrome." (PMID 18154642, 2007). "In addition, CCK administration triggers symptoms, including pain, early satiety, abdominal bloating, nausea, and vomiting, in functional dyspepsia patients." (PMID 35527812, 2022). "For example, lipid-induced release of CCK is upregulated in functional dyspepsia." (PMID 35527812, 2022). "Furthermore, in functional dyspepsia, intravenous administration of CCK increases abdominal pain, nausea, and vomiting." (PMID 35527812, 2022). "Therefore, it is possible that vagal afferent distension signals are enhanced due to the increase in CCK levels, leading to functional dyspepsia symptoms." (PMID 35527812, 2022). "This suggests increased CCK signaling, via chemosensitive vagal afferents, may contribute to the early satiety observed in functional dyspepsia, although other pathways such as the modulatory effect of CCK on mechanosensitive vagal afferents could also be altered in functional dyspepsia." (PMID 35527812, 2022). "Therefore, it is possible that the lipid–CCK–vagal pathway may be altered in functional dyspepsia, contributing to impaired gastric compliance and delayed gastric emptying." (PMID 35527812, 2022). "It should also be noted that pain with CCK does not appear to be specific to gallbladder dysfunction as pain is reproduced with CCK infusion in over half of adult patients with functional dyspepsia who report upper abdominal pain routinely associated with bloating and satiety." (PMID 32266192, 2020). "Fourteen genes corresponding to two gene sets were identified, and the functional dyspepsia-related genes targeted by the activated F. fructus compound were ADRA2A, BDNF, CCK, CRP, GCG, JUN, Kcnh2, PTGS1, PTGS2, Pyy, SLC6A4, and TRPV." (PMID 37375548, 2023). "Between pancreatic fibrosis and functional dyspepsia in the present case series, duodenal mucosa chromogranin-A, a surrogate of enteroendocrine cells, had significantly higher expression in the pancreatic fibrosis group by age-matched comparison, but not cholecystokinin or glucagon-like peptide-1." (PMID 34359334, 2021).
Hyperglycemia (10 papers, 2018 to 2025). An increased concentration of glucose in the blood. "Hyperglycemia has also been reported to suppress the vagovagal reflex that is activated by cholecystokinin and secretin." (PMID 29410956, 2018). "This beneficial effect of HYA on postprandial hyperglycemia might therefore be associated with slowing gastric motility through promotion of the secretion of GLP-1 and CCK." (PMID 39899133, 2025). "Paracrine signaling of CCK is likely more important in β-cell survival pathways than in β-cell function and may be dynamically regulated by hyperglycemia." (PMID 32071395, 2020). "This includes blood glucose from hypoglycemia to hyperglycemia, osmolality, natremia, lipids, proteins, amino acids, and the hormones glucagon, GLP-1, leptin, and CCK." (PMID 33495245, 2021).
malnutrition (10 papers, 2007 to 2025). Inadequate nutrition resulting from poor diet, malabsorption, or abnormal nutrient distribution. "Given cholecystokinin’s role in appetite regulation, elevated levels of CCK-8 have been associated with reduced appetite and food intake in older adults, potentially leading to an increased risk of malnutrition." (PMID 40005054, 2025). "A multivariate model incorporating CCK-8 demonstrated excellent predictive accuracy (AUC = 0.84, 95% CI: 0.77–0.90) and indicated a potential association between elevated CCK-8 levels and a higher risk of malnutrition." (PMID 40005054, 2025). "This study has identified a novel potential correlation between elevated CCK-8 levels and an increased risk of malnutrition." (PMID 40005054, 2025). "CCK-8 levels, centered around a median of 160.60 pg/mL, were marginally associated with the risk of malnutrition, with an odds ratio of 1.01 (95% CI: 1.00–1.01, p = 0.057)." (PMID 40005054, 2025). "In this study, CCK-8 emerged as a key biomarker among those analyzed, showing relevance in evaluating malnutrition risk in elderly individuals." (PMID 40005054, 2025). "A logistic regression model demonstrated that smoking, the utilization of SSRI/MAOI medication, loss of appetite, the risk of frailty syndrome, decreased ASMI, increased VAT, and increased CCK-8 levels were all significant factors for the risk of malnutrition." (PMID 40005054, 2025). "CCK-8 emerged as a strong predictor of malnutrition risk (AUC = 0.58 in females, AUC = 0.64 in males), whereas SIRT-1 (AUC = 0.57 for both sexes), melatonin (AUC = 0.46 for females, AUC = 0.51 for males), and TAC (AUC = 0.42 for females, AUC = 0.54 for males) exhibited weaker predictive abilities." (PMID 40005054, 2025). "The proposed multi-parameter model predicting malnutrition risk confirmed that CCK-8 may play a significant role in the context of malnutrition risk in older people." (PMID 40005054, 2025). "Further research should focus on determining how differences in CCK-8 levels may contribute to the risk of malnutrition in different health states, with interventions to regulate its action." (PMID 40005054, 2025). "The model, incorporating smoking, the intake of SSRI/MAOI medications, the risk of frailty syndrome, loss of appetite according to CNAQ and SNAQ, ASMI, VAT, and CCK-8, achieved a high level of accuracy in predicting malnutrition risk, with an AUC of 0.84 (95% CI: 0.77–0.90)." (PMID 40005054, 2025). "Moreover, malnutrition in patients with HF is associated with decreased appetite‐regulating hormones (cholecystokinin or ghrelin)." (PMID 37434419, 2023). "Although poor appetite is probably a major cause of malnutrition, it is mediated by a variety of factors such as age, several peptide hormones released by the gut including; ghrelin, CCK, peptide-YY, glucagon-like peptide 1, oxyntomodulin, and pancreatic polypeptide and many neurotransmitters." (PMID 30165826, 2018). "This study investigates the potential role of biochemical biomarkers such as sirtuin 1 (SIRT-1), melatonin, cholecystokinin-8 (CCK-8), and total antioxidant capacity (TAC) in identifying the risk of malnutrition." (PMID 40005054, 2025). "Clinically, CCK-8 shows promise, particularly in males, as a biomarker for early malnutrition detection." (PMID 40005054, 2025). "This study explores the relationship between SIRT-1, CCK-8, melatonin, and TAC in the context of malnutrition risk among older adults, addressing an area that has received limited attention." (PMID 40005054, 2025). "This suggests that for every additional pg/mL increase in CCK-8 above 160.60 pg/mL, the odds of malnutrition occurrence increase by approximately 1%." (PMID 40005054, 2025). "In the present study, SIRT-1, melatonin, CCK-8, and TAC were found to have differential diagnostic utility in assessing the risk of malnutrition in elderly individuals." (PMID 40005054, 2025).
malnutrition (continued). "In assessing the predictive value of SIRT-1, cholecystokinin-8, melatonin, and TAC for the risk of malnutrition, optimal cut-off points were established for both male and female participants." (PMID 40005054, 2025). "Malfunction of CCK results in unstable weight regulation and malnutrition seen in 40% of patients with AD, suggesting a link to decreased satiety hormones or decreased sensitivity to these hormones." (PMID 34276354, 2021). "This seems to be related to an impaired secretion of cholecystokinin pancreozymin secondary to enteropathy and/or malnutrition, since normalization of both intestinal mucosa and nutritional status restores the secretion of digestive hormones and enzymes." (PMID 30149525, 2018). "Malnutrition may be due to personal, environmental, and food factors, such as individuals who are more sensitive to cholecystokinin (which suppresses appetite) experiencing faster satiety." (PMID 39935585, 2025). "Furthermore, neonatal overnutrition induced a CCK-resistant phenotype in the offspring, while maternal malnutrition has been shown to reduce CCK levels in the offspring hypothalamus, which may contribute to overweight and metabolic dysfunctions." (PMID 37590249, 2023). "Furthermore, both plasma CCK and PYY concentrations are elevated in patients with chronic nutrient deprivation, malnutrition, and anorexia nervosa, conditions that are known to be associated with a high prevalence of delayed GE." (PMID 18154642, 2007). "Nutritional deprivation is likely to be relevant since inadequate nutritional support is common in critically ill patients, fasting slows GE even in healthy subjects, and fasting CCK and PYY concentrations are higher in patients with anorexia nervosa and malnutrition." (PMID 18154642, 2007).
type 2 diabetes (10 papers, 2016 to 2026). "Here, it was reported that type 2 diabetic patients orally administered with metformin (1,500 mg) or placebo in combination with intravenous infusion of cholecystokinin (CCK) (0.4 mol/kg/min) or saline, showed an enhanced plasma GLP-1." (PMID 32656265, 2020). "It has been suggested that increased anxiety-like behavior in OLETF rats arises from type 2 diabetes and/or the deficit of cholecystokinin (CCK)-1 receptor." (PMID 32938363, 2020). "Moreover, in accordance with the intestinal mucosal CCK concentrations and I‐cell densities in patients with type 2 diabetes, these parameters are also normal." (PMID 40557463, 2025). "Collectively, the purpose of the present study was to clarify whether OLETF rats at the prediabetic and progressive stages of type 2 diabetes show increased anxiety-like behavior, reduced brain areas, and altered numbers of CCK- and PV-positive neurons in the corticolimbic system." (PMID 34506507, 2021). "However, little is known about whether type 2 diabetes affects the expression of CCK in inhibitory and excitatory neurons." (PMID 32938363, 2020). "However, whether more CCK-positive neurons are present in the corticolimbic system in OLETF rats in the prediabetic and progressive stages of type 2 diabetes has not been clarified." (PMID 34506507, 2021).